UBTF (upstream binding transcription factor)
Description:
Recognizes the ribosomal RNA gene promoter and activates transcription mediated by RNA polymerase I (Pol I) through cooperative interactions with the transcription factor SL1/TIF-IB complex. It binds specifically to the upstream control element and can activate Pol I promoter escape.
Synonyms: UBF-1; UBF; UBF1; NOR-90; UBF2; CONDBA
Tractability: PROTAC: ubiquitination databases record sites on it; its protein half-life has been measured.
Gene: Protein-coding gene on chromosome 17 (44,205,033 to 44,221,626, reverse strand). Ensembl gene ENSG00000108312.
Subcellular location: Nucleus, nucleolus
Subcellular location (Human Protein Atlas): Nucleoli fibrillar center
Pathways (Reactome):
Gene expression (Transcription): NoRC negatively regulates rRNA expression; RNA Polymerase I Promoter Escape; RNA Polymerase I Promoter Opening; RNA Polymerase I Transcription Initiation; RNA Polymerase I Transcription Termination
Gene Ontology:
Molecular function: chromatin binding; protein binding; RNA binding; RNA polymerase I cis-regulatory region sequence-specific DNA binding; RNA polymerase I core promoter sequence-specific DNA binding; RNA polymerase I general transcription initiation factor activity; scaffold protein binding
Biological process: regulation of glucose mediated signaling pathway; transcription by RNA polymerase I; transcription initiation at RNA polymerase I promoter; positive regulation of transcription by RNA polymerase I; RNA polymerase I preinitiation complex assembly
Cellular component: fibrillar center; nucleolus; nucleus; nucleoplasm
Genetic constraint (gnomAD): Loss-of-function variants: 8 observed, 108.66 expected, observed/expected ratio (o/e) 0.0736, 90% interval 0.042 to 0.13. The upper end of that interval is the gene's LOEUF score, 0.13, which puts it in group 1 of 6, group 1 being the genes least tolerant of losing a copy. Missense variants: 457 observed, 999.55 expected, observed/expected ratio (o/e) 0.46, 90% interval 0.42 to 0.49. Synonymous variants: 417 observed, 382.77 expected, observed/expected ratio (o/e) 1.09, 90% interval 1 to 1.18.
Gene-disease validity (ClinGen):
ClinGen rates the evidence that UBTF causes each of these diseases.
childhood-onset motor and cognitive regression syndrome with extrapyramidal movement disorder (autosomal dominant): Definitive.
Homologues: Orthologues: chimpanzee UBTF (100% identical), macaque UBTF (100% identical), rat Ubtf (98% identical), guinea pig UBTF (98% identical), mouse Ubtf (98% identical), dog UBTF (95% identical), pig UBTF (93% identical), rabbit UBTF (79% identical), zebrafish ubtf (64% identical), Caenorhabditis elegans hmg-4 (12% identical), Caenorhabditis elegans hmg-3 (12% identical). Paralogues in human: UBTFL1 (26% identical), SSRP1 (16% identical), HMGXB4 (13% identical), SP100 (12% identical), TOX3 (11% identical), SP140 (10% identical), TOX2 (10% identical), HMGB1 (9% identical), TOX4 (9% identical), TOX (9% identical), SP110 (9% identical), HMGB2 (9% identical), and 8 more.
Diseases named in the same sentence as UBTF in open-access papers:
UBTF is named in the same sentence as 59 diseases in open-access papers, as found by Europe PMC text mining. Sharing a sentence is not in itself a finding about the gene and the disease. The quoted sentences say what the papers report.
breast carcinoma (9 papers, 2013 to 2024). "Some studies have reported that UBTF, as a regulator of gene expression, involves in carcinogenesis and progression of a few cancers, such as colorectal cancer, breast cancer, lung cancer, cervical cancer and liver cancer." (PMID 34663332, 2021). "The top autosomal DNAm sites were mapped to genes that have been associated with breast cancer and other malignancies (e.g., cg02325951 on FOXN3, cg20262915 and cg19765154 on NAB1, and cg07850329 on BAG1), as well as childhood neurodegeneration (e.g., cg12607525 on UBTF)." (PMID 36966332, 2023). "Interestingly, previous studies have shown that the suppression of a myeloid leukemia factor (MLF2), an oncogene in breast cancer and myeloid leukemia as well as UBTF which controls rDNA expression contributes significantly to cancers upon promoter hypermethylation." (PMID 34557292, 2021). "Concurrently, irradiated breast cancer cells display localization of GLI1 to the nucleolus as represented by clear colocalization of GLI1 and nucleolar markers UBF (UBTF) and Fibrillarin (FBL)." (PMID 37380890, 2023).
acute myeloid leukemia (6 papers, 2022 to 2024). Acute myeloid leukemia (AML) is a group of neoplasms arising from precursor cells committed to the myeloid cell-line differentiation. "Tandem duplications (TD) of UBTF (UBTF-TD) have also been identified in pediatric acute myeloid leukemia (AML)." (PMID 37600660, 2023). "Tandem duplications (TDs) of the UBTF gene have been recently described as a recurrent alteration in pediatric acute myeloid leukemia (AML)." (PMID 37085611, 2023). "Recently, tandem duplications in exon 13 of UBTF (UBTF-TDs) were identified as novel, recurrent alterations in newly diagnosed and relapsed cases of pediatric acute myeloid leukemia (AML) by a whole genome sequencing approach." (PMID 37236968, 2023). "Very recently, UBTF has been characterized as novel oncogene in acute myeloid leukemia (AML), where internal tandem duplications define a distinct molecular subtype with poor outcome and highest incidence in early adolescents." (PMID 35397658, 2022). "Recently, tandem duplications of UBTF (UBTF-TDs) have been described as a recurrent alteration in pediatric acute myeloid leukemia (AML), accounting for 4% of newly-diagnosed cases and 9% of relapse cases." (PMID 37085611, 2023). "This includes common categories like UBTF, GLISr and GATA1, which were otherwise categorized as “acute myeloid leukemia, myelodysplasia-related” or “acute myeloid leukemia, other defined gene alteration” in the current WHO classification." (PMID 37398194, 2023). "These include common categories like UBTF, GLISr and GATA1, otherwise categorized as ‘AML-MR’ or ‘acute myeloid leukemia with other defined gene alterations’ in the current WHO classification." (PMID 38212634, 2024).
melanoma (5 papers, 2021 to 2023). A malignant, usually aggressive tumor composed of atypical, neoplastic melanocytes. "The data showed that UBTF expression was observably increased in melanoma and the high UBTF expression was associated with clinical pathological characteristics." (PMID 34663332, 2021). "These include UBTF upregulation in solid tumors such as melanoma, lung and colon cancers, or the oncogenic gene fusions UBTF::ETV4 in prostate cancer and UBTF::ATXN7L3 in B-cell precursor acute lymphoblastic leukemia." (PMID 37085611, 2023). "According to TCGA analysis data, RAB34 expression is increased in high-grade glioblastoma compared to lower grades, and UBTF is increased in melanoma compared to normal skin." (PMID 37689310, 2023). "UBTF shRNA remarkably suppressed melanoma cell growth, as evidenced by MTT and colony formation assays (p < 0.01)." (PMID 34663332, 2021). "It was demonstrated that UBTF promoted GIT1 expression in melanoma cells through binding to the promoter region of GIT1." (PMID 34663332, 2021). "Here we reported that UBTF mRNA and protein expressions were upregulated in primary melanoma specimens and cell lines." (PMID 34663332, 2021). "It was verified that UBTF promoted GIT1 transcription in melanoma cells through binding to the promoter region of GIT1." (PMID 34663332, 2021). "It was also found that silencing UBTF downregulated Bcl-2 protein expression and upregulated Bax protein expression in melanoma cell, whereas UBTF overexpression increased Bcl-2 expression and decreased Bax expression." (PMID 34663332, 2021). "Results from MTT assays revealed that silencing UBTF significantly restrained melanoma cell proliferation at 48 and 72 h after transfection (p < 0.01), whereas UBTF overexpression observably promoted melanoma cell multiplication (p < 0.01)." (PMID 34663332, 2021). "The qRT-PCR results showed that UBTF mRNA level was significantly increased in 80.3% (53/66) of the melanoma tissues compared to the normal tissues (p < 0.001)." (PMID 34663332, 2021). "UBTF promotes melanoma cell proliferation and cell cycle progression by facilitating GIT1 transcription, thereby activating MEK1/2-ERK1/2 signalling pathways." (PMID 34663332, 2021). "The Cancer Genome Atlas (TCGA) data revealed that the UBTF expression was observably upregulated in melanoma samples compared with normal skin tissues (p < 0.001)." (PMID 34663332, 2021). "In this study, we detected the UBTF expression level in 66 melanoma sufferers, and explored the function and corresponding mechanisms of UBTF in modulating melanoma progression." (PMID 34663332, 2021). "To investigate the function of UBTF in melanoma progression, we analyzed and detected UBTF expression in melanoma specimens and cell lines." (PMID 34663332, 2021). "TCGA data showed that UBTF expression was positively related with GIT1 expression in human melanoma tissues (n = 469, r = 0.39, p < 0.001)." (PMID 34663332, 2021). "We found that UBTF is overexpressed and related to the clinicopathologic characteristics of melanoma patients." (PMID 34663332, 2021). "The qRT-PCR results also showed that UBTF mRNA expression was remarkably positively correlated with GIT1 mRNA expression in melanoma (n = 66, r = 0.4313, p < 0.001, Pearson’s correlation)." (PMID 34663332, 2021). "Nevertheless, the function of UBTF in many kinds of tumors, including melanoma, hasn’t been investigated exactly." (PMID 34663332, 2021). "This study revealed that UBTF was upregulated in melanoma and was related to clinicopathologic characteristics." (PMID 34663332, 2021). "Our data confirmed that UBTF facilitates melanoma cell proliferation and cell cycle progression by promoting GIT1 transcription, thereby activating MEK1/2-ERK1/2 signalling pathways." (PMID 34663332, 2021). "Cell viability assay showed that silencing UBTF inhibited melanoma cell multiplication, overexpressing GIT1 rescued the effect of UBTF siRNA-1 on cell growth (p < 0.01)." (PMID 34663332, 2021).
melanoma (continued). "In order to further analyze the molecular mechanism of UBTF regulating melanoma progression, UBTF target gene was predicted by bioinformatics analysis (UCSC Genome Browser)." (PMID 34663332, 2021). "UBTF overexpression facilitated melanoma cell proliferation and cell cycle progression and restrained." (PMID 34663332, 2021). "The rescue studies demonstrated that UBTF facilitated melanoma cell proliferation, cell cycle progression, and inhibited apoptosis through promoting GIT1 transcription." (PMID 34663332, 2021). "ChIP-RT-PCR assay also confirmed that UBTF bound to the promoter (Primer 6) of GIT1 in melanoma cells." (PMID 34663332, 2021). "Our study demonstrates that UBTF promotes melanoma cell proliferation and cell cycle progression by promoting GIT1 transcription, thereby activating MEK1/2-ERK1/2 signalling pathways." (PMID 34663332, 2021). "The UBTF mRNA expression was also markedly upregulated in melanoma cell lines (Mel-RM, A375 and SK-MEL-28) than in human keratinocyte HaCaT cells (p < 0.001)." (PMID 34663332, 2021). "UBTF facilitated melanoma cell proliferation in vitro and in vivo, and the promotion was achieved through promoting cell cycle G1-S phase transition." (PMID 34663332, 2021). "Similarly, POLR1B knockdown induces lung cancer cell apoptosis, VPS72 knockdown inhibits the proliferation, invasion, and migration of hepatocellular carcinoma (HCC) cells, and UBTF silencing suppresses melanoma cell proliferation." (PMID 37444571, 2023). "In melanoma, UBTF has been shown to act as cell cycle regulator." (PMID 36231068, 2022). "The UBTF protein expression was significantly upregulated in melanoma tissues and cell lines." (PMID 34663332, 2021). "Overexpression of GIT1 eliminated the effects of silencing UBTF on melanoma cells." (PMID 34663332, 2021). "UBTF expression was positively related with GIT1 expression in human melanoma tissues." (PMID 34663332, 2021). "Tumor formation assay was used to analyze the effect of UBTF on melanoma growth." (PMID 34663332, 2021). "The findings indicate that UBTF play a crucial function in melanoma." (PMID 34663332, 2021). "In summary, this study demonstrates that UBTF functions as an oncogene in melanoma." (PMID 34663332, 2021). "The findings indicate that UBTF plays a crucial function in melanoma and may be a potential therapeutic target for the treatment of this disease." (PMID 34663332, 2021). "UBTF facilitated melanoma cell proliferation and suppressed apoptosis." (PMID 34663332, 2021). "The findings demonstrated UBTF as a transcriptional regulator of GIT1 in human melanoma cells." (PMID 34663332, 2021). "This study suggests that UBTF plays a crucial function in melanoma and may be a potential therapeutic target for the treatment of this disease." (PMID 34663332, 2021). "Hence, we further research the molecular mechanism of UBTF modulation in human melanoma." (PMID 34663332, 2021). "Moreover, the high UBTF expression was associated with melanoma thickness, lymph node metastasis and initial stage." (PMID 34663332, 2021). "The results indicated that UBTF might be involved in human melanoma progression." (PMID 34663332, 2021). "Our results showed that UBTF could restrain melanoma cell apoptosis." (PMID 34663332, 2021). "To explore the possible molecular mechanism of UBTF regulation in melanoma, we fulfilled bioinformatics predicting, ChIP-qRT-PCR and reporter gene assay, through which we ascertained GIT1 as UBTF targeting gene." (PMID 34663332, 2021). "MTT and colony formation assays were used to investigate the effects of UBTF and GIT1 on melanoma cell proliferation." (PMID 34663332, 2021). "UBTF and GIT1 expressions in melanoma specimens and cell lines were examined by quantitative real-time PCR (qRT-PCR) and Western blot." (PMID 34663332, 2021). "Nevertheless, the the biological function and potential molecular mechanism of UBTF in melanoma are still not clear and need to be clarified." (PMID 34663332, 2021).
Brain atrophy (4 papers, 2022 to 2025). Partial or complete wasting (loss) of brain tissue that was once present. "Missense variants in UBTF (encoding UBF) also result in childhood-onset neurodegeneration with brain atrophy (CONDBA), which causes neuro-regression from very early in life." (PMID 40366093, 2025). "A de novo, pathogenic, missense variant in UBTF, c.628G>A p.Glu210Lys, has been described as the cause of an emerging neurodegenerative disorder, Childhood‐Onset Neurodegeneration with Brain Atrophy (CONDBA)." (PMID 36106513, 2022). "UBTF is a key gene related to neurodegenerative diseases and brain atrophy." (PMID 37525090, 2023). "A recurrent, de novo pathogenic variant in UBTF (upstream binding transcription factor) (OMIM 600673), c.628G>A p.Glu210Lys (NM_014233.3), has been associated with childhood‐onset neurodegeneration with brain atrophy (CONDBA, OMIM 617672)." (PMID 36106513, 2022).
leukemia (4 papers, 2023 to 2025). A malignant (clonal) hematologic disorder, involving hematopoietic stem cells and characterized by the presence of primitive or atypical myeloid or lymphoid cells in the bone marrow and the blood. "Categories with acute megakaryoblastic or erythroid leukemia (AMKL/AEL) phenotypes are clearly enriched in infants, whereas CBF leukemias and mutation-defining leukemias (e.g., UBTF, NPM1, CEBPA) were enriched in adolescents and young adults." (PMID 37398194, 2023). "Categories with acute megakaryoblastic leukemia (AMKL) or acute erythroid leukemia (AEL) phenotypes are clearly enriched in infants, whereas CBF leukemias and mutation-defined leukemias (for example, UBTF, NPM1, CEBPA) were enriched in adolescents and young adults." (PMID 38212634, 2024). "The observed anti-leukemic activity of SNDX-5613 in UBTF-TD leukemia cells is likely due to the repression of pro-leukemic gene expression, as UBTF-TDs colocalize with menin and MLL at multiple genomic loci, including those implicated in leukemia." (PMID 39336822, 2024). "In addition to its established oncogenic roles in MLLr and NPM1 mutant leukemias, menin may also play a role in NUP98 fusion and UBTF tandem duplication (UBTF-TD) acute leukemias." (PMID 39336822, 2024).
cardiac hypertrophy (3 papers, 2021 to 2024). "Upstream binding transcription factor (UBTF) has been shown to regulate PolI transcription activity in cardiac hypertrophy." (PMID 34977198, 2021).
glioma (3 papers, 2022 to 2023). A benign or malignant brain and spinal cord tumor that arises from glial cells (astrocytes, oligodendrocytes, ependymal cells). "Our data confirm that in gliomas, during the formation of neurospheres, the activation of UBTF commonly leads to an increase in the mRNA level of the key component of mTORC2—RICTOR." (PMID 36231068, 2022). "Transcripts of VV-GMCSF-Lact-infected glioma and NB cells that directly correlate with CD50 are enriched with mRNAs controlled by transcription factors ATF2, BRCA1, CREB1, ELF1, TAF1, UBTF, and YY1." (PMID 37998351, 2023). "It was observed that NS formation is accompanied by the activation of five common gliomas of TFs, SOX2, UBTF, NFE2L2, TCF3 and STAT3." (PMID 36231068, 2022). "In addition, we revealed the involvement of transcription factors UBTF and NFE2L2, which, to the best of our knowledge, have not been previously associated with the formation of aggressive forms, invasion, and metastasis of gliomas." (PMID 36231068, 2022).
Myelodysplasia (3 papers, 2023). Clonal hematopoietic stem cell disorders characterized by dysplasia (ineffective production) in one or more hematopoietic cell lineages, leading to anemia and cytopenia.
acute leukemia (2 papers, 2024 to 2025). A clonal (malignant) hematopoietic disorder with an acute onset, affecting the bone marrow and the peripheral blood. "Lastly, the clinical application of menin inhibitors is gradually expanding to include other acute leukemia subtypes characterized by MEIS1-HOXA axis activation, such as specific AML subgroups with particularly poor prognosis like NUP98-r, DEK-NUP21, and UBTF-TD." (PMID 40710017, 2025).
colon cancer (2 papers, 2023 to 2025). "Given UBTF’s essential role in ribosomal RNA transcription, it’s unsurprising that its knockdown has previously been shown to suppress colon cancer cell proliferation." (PMID 39886381, 2025).
colorectal cancer (2 papers, 2021 to 2024). A primary or metastatic malignant neoplasm that affects the colon or rectum. "It is found that S6K-mediated UBTF promotes colorectal cancer cell proliferation by facilitating the transcription ribosomal DNA." (PMID 34663332, 2021).
lung carcinoma (2 papers, 2021 to 2023). "It was reported that UBTF expression upregulated in lung cancer specimens." (PMID 34663332, 2021).
prostate carcinoma (2 papers, 2023). A carcinoma that arises from epithelial cells of the prostate gland. "Biased towards African-specific drivers (63 versus 9 shared), many are novel to prostate cancer (18/63), including several putative therapeutic targets (CHD7, DPF3, POLR1B, SETD1B, UBTF, and VPS72)." (PMID 37444571, 2023).
acute lymphoblastic leukemia (1 paper, 2025). Leukemia with an acute onset, characterized by the presence of lymphoblasts in the bone marrow and the peripheral blood. "KMT2Ar can appear in acute lymphoblastic leukemia (ALL) as well as in some rare but difficult-to-treat ALs, such as those harboring upstream binding transcription factor (UBTF) tandem duplications, Nucleoporin 98 (NUP98) rearrangements (NUP98r) and mixed phenotypes (MPAL)." (PMID 39796769, 2025).